GBP5 (guanylate binding protein 5)
Diseases named in the same sentence as GBP5 in open-access papers (continued):
Sharing a sentence is not in itself a finding about the gene and the disease.
tumor (continued). "Future studies to clarify how GBP5 functions in OSCC proliferation, invasion, and tumor immune mechanisms will provide new insights into a series of paradigms of chronic inflammation and carcinogenesis." (PMID 38978333, 2024). "While some genes such as GBP5 and RAC2 are predominantly expressed in immune cells (T cells and myeloid cells), other signature genes exhibited universal expression in both tumor cells and immune or stromal compartments." (PMID 37587913, 2023). "The findings of co-staining of F4/80, GBP5, and iNOS were crucial evidence that DHA remodels TAM into an M1 phenotype in tumor tissues." (PMID 36034842, 2022). "GBP5 and PSMB10 have been reported in tumors as part of the downstream interferon genes and are also considered to be the coordinators of tumor disease immunity." (PMID 34220795, 2021). "After identifying the prognostic value and expression level of CASKIN1, EMR3, and GBP5, we performed correlation analysis between CASKIN1, EMR3, and GBP5 expression levels and immune/stromal/Estimate scores, and tumor purity in HCC, respectively." (PMID 33897701, 2021). "We analyzed the role of ICDRs in tumor immune microenvironment by using the previous data of single cell transcriptome, and we analyzed the distribution of several key genes (PSME2, TYMP, KLHDC7B, GBP5, EPSTI1, STAT1 and OAS2) in different cell types." (PMID 40259929, 2025). "This study showed that GBP5 expression in the tumor and stroma did not affect survival; however, patients with low GBP5 expression in the tumor and high GBP5 expression in the stroma had a better prognosis than other patients." (PMID 38978333, 2024). "GBP5, a member of the TRAFAC class dynamin-like GTPase superfamily, is involved in inflammasome assembly and innate immunity, and promotes M1 macrophage polarization, suggesting potential roles in enhancing anti-tumor immunity." (PMID 39355255, 2024). "GBP5 has long been recognized as a proinflammatory mediator, frequently studied in the context of inflammatory diseases rather than tumor research 40-42." (PMID 38817865, 2024). "Consistently, in vivo experiments showed significant upregulation of iNOS, GBP5, and MHC-II in tumor grafts of LLC-bearing mice that received Ce6 PDT, suggesting that more M1-phenotype macrophages may be present in tumor tissues." (PMID 35308251, 2022). "Importantly, the tumor tissue of mice treated with DHA showed enhanced iNOS, GBP5, and MHC-II expression, indicating the M1 reprogramming of TAM inside the tumor tissue." (PMID 36034842, 2022). "We also explored the correlation between GBP5 and immunotherapy and found that CRC may be an appropriate tumor type to target GBP5." (PMID 36246628, 2022). "On the contrary, the expressions of GBP3, GBP4, and GBP5 in tumor tissues were significantly higher than those in normal tissues." (PMID 36246628, 2022). "In vivo data overall agreed with the in vitro results, showing increased expression of CD80, CD86, MHC-II, and GBP5 indicative of M1-like activation in tumor grafts not depleted of macrophages." (PMID 34488792, 2021). "Through next generation sequencing for tumor tissues of OSCC patients, the gene expression level of guanylate binding protein 5(GBP5) was significantly elevated in tumor tissues compared with adjacent normal tissues and associated with poor prognosis in OSCC patients." (PMID 34439200, 2021). "Moreover, GBP5 gradually increased from normal tissues, to CTAN tissues, to tumor tissues in BMSCC and TSCC patients." (PMID 34439200, 2021). "Our results showed that higher mRNA expressions of GBP5 in HNSCC tissues and may related with patients’ tumor immune microenvironment." (PMID 32269280, 2020). "Moreover, we conducted in vitro experiments to prove that, exogenous overexpression of GBP5 in T cells fails to augment their tumor-killing efficacy, while elevated GBP5 expression in OC cells does not directly enhance the secretion of GZMB and IFNγ from T cells." (PMID 38817865, 2024).
bacterial infection (6 papers, 2019 to 2024). "It would be of interest to perform functional assays to confirm if functions remain conserved, for example, both human and mouse GBP5 have been implicated in the NLRP3 activation upon bacterial infection." (PMID 38357541, 2024). "From the gene-pathway analysis of our RNA-seq data between the WT_DSS and Gbp5−/−_DSS mice, we noticed a significant enrichment of genes involved in bacterial infection." (PMID 39062588, 2024). "Indeed, GBP2 and GBP5 appear to have important roles against viral and bacterial infections and to induce immune responses in mouse and humans." (PMID 35222365, 2022). "During bacterial infection, multiple mouse Gbps, human GBP2, and GBP5 support the activation of caspase‐1‐containing inflammasome complexes or caspase‐4 which trigger pyroptosis." (PMID 31268602, 2019). "Further study is required to clarify potential collaborative roles of caspase-11 and GBP5 in IBD pathogenesis, and whether viral or bacterial infection triggers elevated GBP5 expression in the intestines of IBD." (PMID 35722277, 2022).
respiratory diseases (2 papers, 2025). "Consequently, the lack of GBP5 can be expected to parlay into increased risk of pathogen susceptibility, including pathogens associated with respiratory diseases." (PMID 41473269, 2025). "Additionally, in respiratory diseases such as COPD, the RNA-binding protein Alpha-2-Glycoprotein 1 (AZGP1) downregulates GBP5, modulating epithelial hyperplasia during disease progression." (PMID 40788157, 2025).
gastrointestinal tumors (1 paper, 2022). "In addition, in other gastrointestinal tumors such as STAD and READ, GBP5 also tend to be lower expressed in M1 stage samples, which is consistent with the effect of GBP5 on patient prognosis." (PMID 36246628, 2022).
infectious disease (1 paper, 2025). A disorder directly resulting from the presence and activity of a microbial, viral, or parasitic agent in humans. "In infectious diseases, such as Mycobacterium tuberculosis (Mtb) and human immunodeficiency virus (HIV), GBP5 modulates disease progression through various anti-pathogenic pathways." (PMID 40788157, 2025).
neurological disorders (1 paper, 2025). "For example, synthetic steroid 5α-Androst-3β has been shown to inhibit the GBP5/NLRP3 axis, reducing microglial activation and pro-inflammatory cytokine release, thereby protecting neurons in neurological disorders." (PMID 40788157, 2025).
vasculopathy (1 paper, 2024). "Among these macrophages, the Gbp5+ Mφ subpopulation was markedly increased in the PVAT of T2DM rats and potentially played proinflammatory roles in T2DM vasculopathy." (PMID 39627688, 2024).
GBP5 also shares sentences with these, for which no sentence is quoted: influenza (3 papers); cutaneous melanoma (2); immune system diseases (2); Arthritis (1); autoimmune disease (1); bacteremia (1); breast tumors (1); childhood asthma (1); co-infection (1); colon cancer (1); esophageal squamous cell carcinoma (1); gastrointestinal infection (1); gastrointestinal stromal tumor (1); head and neck cancer (1); Hepatic fibrosis (1); Immunodeficiency (1); infectious mononucleosis (1); intestinal inflammation (1); ischemic cardiomyopathy (1); leishmaniasis (1); leukemia (1); lung adenocarcinoma (1); lung diseases (1); lupus nephritis (1); nasal polyps (1); pancreatic adenocarcinoma (1); pancreatic cancer (1); peritonitis (1); phlebitis (1); pregnancy disorder (1).
A further 7 diseases each share a sentence with GBP5 in 1 paper.